FTO (FTO alpha-ketoglutarate dependent dioxygenase)
Diseases named in the same sentence as FTO in open-access papers (continued):
Sharing a sentence is not in itself a finding about the gene and the disease.
cervical cancer (37 papers, 2017 to 2025). A primary or metastatic malignant neoplasm involving the cervix. "Overall, it offers the possibility of FTO for a clinical diagnostic and therapeutic target in cervical cancer." (PMID 33029866, 2020). "As FTO is frequently overexpressed in human cervical cancer tissues, we then explored the detail function of FTO in tumorigenesis with loss-of-function study by introducing two FTO specific small hairpin RNAs (shRNAs) into Hela cells, respectively." (PMID 31827395, 2019). "Notably, the malignancy-associated behaviors of cervical cancer cells undergoing FTO knockdown are significantly modified by the compensatory overexpression of ZEB1, which mitigates these effects." (PMID 39175477, 2024). "FTO is frequently overexpressed in cervical cancer and associated with cervical cancer progression." (PMID 33029866, 2020). "Furthermore, we also observed the migration capacity of Hela and SiHa cells was dramatically impaired when FTO was deficient, indicating FTO was an important factor which positively regulated cervical cancer cells’ proliferation and migration." (PMID 31827395, 2019). "Thus, it can be seen that, the increase in FTO may be caused by HPV integration in cervical cancer, and it plays a cancer‐promoting role in cervical cancer." (PMID 39692250, 2024). "For example, in cervical cancer, FTO regulates m6A methylation of ZEB1 and Myc, key oncogenes involved in cell proliferation and migration." (PMID 41141648, 2025). "The amount of FTO mRNA in cervical cancer tissue (N = 304) was lower than that in normal cervical tissue (N = 3), according to one research based on data analysis of cervical cancer tissue samples in TCGA." (PMID 40919129, 2025). "In cervical cancer, FTO-mediated demethylation regulates the expression of β-catenin and promotes the activity of Excision Repair Cross-Complementation Group 1 (ERCCI), which makes cervical squamous carcinoma resistant to chemoradiotherapy." (PMID 40469197, 2025). "FTO knockdown inhibited the proliferation and migration of HeLa and SiHa cells, while overexpression of FTO promoted chemical resistance of cervical cancer cells." (PMID 40919129, 2025). "has demonstrated that BMP4 treatments not only encourage the growth of cervical cancer cells in vitro but also effectively inhibit the Hippo/YAP1/TAZ signaling pathway by reducing FTO levels." (PMID 39175477, 2024). "This suppression illustrates the potential of FTO as an oncogenic facilitator, suggesting its significance in the molecular pathology of cervical cancer." (PMID 39175477, 2024). "To further illustrate that PIK3R3 and p‐AKT is regulated by FTO in cervical cancer cells, we transfected control plasmid and PIK3R3 plasmid into SiHa‐lv‐shFTO cells, respectively." (PMID 39692250, 2024). "Among C33A, Hela, SiHa, S12, and CaSki cells, the expression level of FTO in SiHa cells was significantly higher than that in other cervical cancer cells, while the expression level of CaSki cells was the lowest." (PMID 39692250, 2024). "has elucidated that FTO directly influences the dynamics of cervical cancer cell migration and proliferation through its interactions with key molecular players such as E2F1 and Myc mRNA." (PMID 39175477, 2024). "More importantly, we found that the FTO knockdown can inhibit the proliferation and metastasis of cervical cancer cells in vitro and vivo." (PMID 39692250, 2024). "FTO is strongly correlated with cervical cancer progression and is overexpressed in human cervical cancer tissues." (PMID 39175477, 2024). "After changing the FTO expression level by lentivirus transfection, the proliferation and metastasis ability of cervical cancer cells were detected both in vitro and in vivo." (PMID 39692250, 2024). "Western blot showed that when the expression level of FTO in cervical cancer cells was downregulated, the expressions of PIK3R3 were also decreased, as well as p‐AKT." (PMID 39692250, 2024).
cervical cancer (continued). "Recent studies have increasingly pointed to FTO’s involvement in cervical cancer, suggesting its role in influencing the disease’s progression, as documented in several pieces of research." (PMID 39175477, 2024). "Functional assays indicated that FTO promoted the proliferation, migration and invasion of cervical cancer cells both in vitro and in vivo." (PMID 39692250, 2024). "Our study aimed to narrate the biological function and potential mechanisms for FTO in cervical cancer malignancy." (PMID 39692250, 2024). "And the results exemplified that the upregulation of FTO can reduce m6A modification level in cervical cancer cells." (PMID 39692250, 2024). "FTO is associated with multiple genes affecting proliferation, migration, EMT, glycolysis, and sensitivity to radiotherapy in cervical cancer cells." (PMID 39175477, 2024). "The CCK8 assay and Ki67 assay showed that cervical cancer cells grew relatively slowly after FTO down‐regulation, in contrast, FTO overexpression facilitated the proliferative ability." (PMID 39692250, 2024). "In this study, we aimed to identify the novel role of FTO‐dependent m6A modification in cervical cancer malignancy, as well as the profiled m6A transcriptome‐wide mapping." (PMID 39692250, 2024). "Our experimental results showed that FTO is highly expressed in cervical cancer and predicts the late FIGO stage." (PMID 39692250, 2024). "Our data verified that PIK3R3 overexpression can partially reverse the inhibitory effect of FTO knockdown on proliferation, migration and invasion of cervical cancer cells." (PMID 39692250, 2024). "Our experiment displayed that FTO can promote proliferation and migration in cervical cancer cells, and upregulation of PIK3R3 can partially neutralize the effect of FTO‐knockdown." (PMID 39692250, 2024). "FTO’s influence on BMP4 regulation indicates a profound indirect contribution to the progression of cervical cancer, observable in both controlled laboratory settings and clinical scenarios." (PMID 39175477, 2024). "All these results suggested that FTO facilitated cervical cancer malignancy through inducing m6A‐demethylation of PIK3R3 mRNA." (PMID 39692250, 2024). "IHC assay was used to detect the expression of FTO protein in forty‐three pairs of FIGO stage II cervical cancer tissues and paracancerous tissues." (PMID 39692250, 2024). "It is therefore imperative to conduct further investigations to unravel the precise mechanisms by which FTO impacts glycolysis in the context of cervical cancer and to examine the interactions between FTO and various regulators of glucose metabolism." (PMID 39175477, 2024). "Given its significant role in these diverse processes, FTO is a promising target for the detection and management of gynecological tumors including ovarian, endometrial, and cervical cancers." (PMID 39175477, 2024). "All in all, these data suggest a vital role for FTO in occurrence and development of cervical cancer." (PMID 39692250, 2024). "The regulatory mechanisms of FTO within the context of cervical cancer have emerged as a crucial area of investigation." (PMID 39175477, 2024). "In order to further confirm the effects of FTO on m6A modification, we respectively constructed cervical cancer cells with FTO knockdown or overexpression." (PMID 39692250, 2024). "For example, FTO is overexpressed in human cervical cancer tissues and facilitates the proliferation, migration, and invasion of human cervical cancer cells." (PMID 37175660, 2023). "In cervical cancer, FTO enhanced resistance to chemo- and radiotherapy through altered ß-catenin expression caused by m6A demethylation." (PMID 35731272, 2023). "With the exception of FTO, the expression levels of m6A regulators in cervical cancer were much greater than in normal tissues." (PMID 36091006, 2022). "PD-L1 expression increased dramatically in cervical cancer tissues and was significantly linked to ALKBH5, FTO, METTL3, RBM15B, YTHDF1, YTHDF3, and ZC3H13 expression levels." (PMID 36091006, 2022).
cervical cancer (continued). "A study in cervical cancer suggested that FTO regulates migration by promoting the protein translation of E2F1 and MYC, two regulators of cell cycle and migration, in an m6A-dependent manner." (PMID 35350378, 2022). "In cervical cancer, FTO enhances the chemoradiotherapy-resistance by reducing the m6A modification of β-catenin." (PMID 34281544, 2021). "For example, FTO plays an important oncogenic role in regulating the proliferation and migration of cervical cancer cells through m6A modification that controls E2F1 and Myc transcription." (PMID 33952279, 2021). "In cervical cancer, FTO can activate the β-catenin pathway and increase ERCC1 expression that is associated with worse prognosis." (PMID 33461542, 2021). "FTO is also upregulated in cervical cancer where it induces resistance to chemo-radiotherapy and enhances the response to DNA damage." (PMID 33461542, 2021). "FTO contributes to the proliferation and migration of cervical cancer cells by directly interacting with E2F1 and MYC transcripts and impairing their translation efficiency in a demethylase‐dependent manner." (PMID 33029866, 2020). "FTO serves as an oncogenic regulator for cervical cancer cells’ proliferation and migration which is vastly depended on its demethylase activity." (PMID 31827395, 2019). "In this study, we aim to explore the expression of FTO and its correlation with cervical cancer progression, moreover, we sought to uncover the detail molecular mechanisms on how FTO regulate cervical cancer progression." (PMID 31827395, 2019). "In this study, we first analyzed the expression of FTO in two independent human cancer datasets and evaluated the correlation between FTO level and cervical cancer progression." (PMID 31827395, 2019). "Our data suggested that FTO was frequently overexpressed in human cervical cancer tissues and highly correlated with cervical cancer progression." (PMID 31827395, 2019). "We therefore provide direct evidence that targeting FTO signaling represents a promising strategy for cervical cancer therapy." (PMID 31827395, 2019). "Taken together, our study demonstrates that the m6A demethylase FTO plays an important role in regulating cervical cancer cell proliferation and migration, the oncogenic function of FTO is dependent on its demethylase activity." (PMID 31827395, 2019). "In line with previous studies, our study also identified FTO acted as an oncogenic factor which regulated cervical cancer cells’ proliferation and migration, thus, FTO becomes a potential target for cancer therapy which attracts intense research interest." (PMID 31827395, 2019). "Using small hairpin RNA technology, we explored the function of FTO in cervical cancer cell line Hela and SiHa cells, respectively." (PMID 31827395, 2019). "To get an overview of FTO’s expression pattern in human cervical cancer tissues, we first examined FTO’s protein levels in different human cancer tissues by analyzing two independent human datasets HPA041086 and HPA068695." (PMID 31827395, 2019). "Our study indicates that FTO plays important oncogenic role in regulating cervical cancer cells’ proliferation and migration via controlling m6A modification of E2F1 and Myc transcripts." (PMID 31827395, 2019). "Another research that has been mentioned came to the conclusion that FTO transcripts were strongly expressed in cervical cancer tissues (N = 20) compared with normal cervical tissues (N = 50) based on its own examination of clinical tissue samples that were obtained." (PMID 40919129, 2025). "Studies on the effects of FTO in cervical cancer, however, are inconsistent and hotly debated." (PMID 40919129, 2025). "However, there is still a lack of studies explaining how FTO acts on HK2 and what pathway FTO regulates cervical cancer cell proliferation through HK2-mediated." (PMID 39175477, 2024).
cervical cancer (continued). "Additionally, enhanced expression of the FTO gene within the SiHa cervical cancer cell line has been shown to lead to a reduction in m6A methylation." (PMID 39175477, 2024). "What's more, FTO is highly expressed in cervical cancer and predicts the late FIGO stage." (PMID 39692250, 2024). "Therefore, we take PIK3R3 as the breakthrough point to further explore the mechanism of FTO promoting the proliferation and metastasis of cervical cancer." (PMID 39692250, 2024). "In cervical cancer, FTO was found to promote MYC translation; however, whether this mechanism was m6A-dependent was not established." (PMID 35350378, 2022). "Studies have shown that FTO is a potential candidate for the treatment of cervical cancer." (PMID 33952279, 2021). "Patients with cervical cancer and co‐expression of FTO and β‐catenin have a worse prognosis." (PMID 33029866, 2020). "Low m6A level, as an independent prognostic indicator, was found to be associated with cancer progression and poor outcome through screening 286 cervical cancer samples, and augmenting m6A modification with the FTO inhibitor MA2 suppressed the tumour development in mouse models." (PMID 33029866, 2020). "The FTO’s expression was efficiently suppressed, resulting in obvious upregulation of global mRNA m6A level and significant inhibition of cell proliferation; the similar effect was reproduced with another human cervical cancer cell line, SiHa cells." (PMID 31827395, 2019). "Next, using in-house collected cervical cancer samples, we investigated the relative transcription difference of FTO between normal cervices and cervical cancer tissues, indeed, our data revealed that FTO was significantly higher expressed in cervical cancer tissues than normal controls." (PMID 31827395, 2019). "We next questioned whether FTO’s RNA demethylase activity was essential to play its oncogenic role in cervical cancer tumorigenesis." (PMID 31827395, 2019). "Indeed, FTO’s high expression was more frequently identified in cervical cancer tissues compared to many other cancer subtypes." (PMID 31827395, 2019). "FTO represents a potential drug candidate for cervical cancer therapy." (PMID 31827395, 2019). "Therefore, targeting FTO could enhance the efficacy of radiotherapy in the treatment of cervical cancer." (PMID 39175477, 2024). "This suggests that elevated FTO expression may contribute to the progression of cervical cancer." (PMID 39175477, 2024). "Similarly, ecotopic expression of E2F1 or Myc could significantly increase FTO competent cervical cancer cells’ migration compare to control cells." (PMID 31827395, 2019). "HK2 can be directly mediated by the m6A modifiers METTL3, YTHDF1, IGF2BP2, FTO and ALKBH5 in colorectal cancer and cervical cancer, leading to increased glycolysis, upregulated aerobic respiration in mitochondria and tumor progression." (PMID 41373022, 2025). "The results evoked that upregulation of FTO promoted the translation of PIK3R3, which enhanced the activation of FoxO pathway and facilitates cervical cancer malignancy." (PMID 39692250, 2024). "Taking our findings together, the upregulation of m6A demethylase FTO decreases m6A modification of PIK3R3 mRNA, which increases PIK3R3 levels and activates FoxO pathway, thus facilitating cervical cancer malignancy." (PMID 39692250, 2024). "In order to systematically study the role of FTO in cervical cancer, we searched GSE44001 data and found that FTO was significantly up‐regulated in FIGO stage II cervical cancer patients, compared with stage I (p < 0.05)." (PMID 39692250, 2024). "In cervical cancer, the MYC protein was recently identified as a direct substrate of the m6A demethylase FTO and FTO-mediated demethylation boosts the translational efficiency of MYC mRNA." (PMID 38273337, 2024). "FTO also interacts with the transcription of E2F1 and myc to promote the proliferation and migration of cervical cancer cells." (PMID 35581263, 2022).
cervical cancer (continued). "FTO can control the m6A modification of E2F1 and Myc transcripts to regulate the proliferation and migration of cervical cancer cells." (PMID 36058934, 2022). "Mechanistically, FTO directly interacted with E2F1 and Myc mRNAs and inhibition FTO dramatically impaired these two important oncogenes’ translation, thus suppressed cervical cancer cells’ proliferation and migration." (PMID 31827395, 2019). "However, the role of FTO in cervical cancer tumorigenesis remains unclear." (PMID 31827395, 2019). "Knockdown of erasers (FTO and ALKBH5) or overexpression of writers (METTL3 and METTL14) suppressed the cellular proliferation and tumor formation of cervical cancer cells both in vitro and in vivo." (PMID 31711514, 2019). "On the other hand, knocking-down adenosine demethylases (FTO and ALKBH5) or overexpressing adenosine methyltransferases (METTL3 and METTL14) suppressed cervical cancer development in vivo." (PMID 29228737, 2017). "Subsequent investigations as reported by Cancer Cell International, found that patients with advanced stages of cervical cancer (stages III and IV) exhibited significantly higher expression of FTO than those in the early stages (stages I and II) or those with a normal cervix." (PMID 39175477, 2024). "Based on TCFA‐CESC cohort, the FTO expression level in HPV positive cervical cancer patients is higher than that of HPV negative cervical cancer patients." (PMID 39692250, 2024). "After knocking down FTO, upregulation of PIK3R3 can restore the malignancy of cervical cancer." (PMID 39692250, 2024). "Given all of that, the increase in FTO may be related to HPV integration and predicts the late FIGO stage in cervical cancer." (PMID 39692250, 2024). "For example, FTO, METTL3, and YTHDF1 could promote the progression and metastasis of cervical cancer and are potential biomarkers for the prognosis of cervical cancer." (PMID 35432630, 2022). "Furthermore, FTO and MYC have also been found to cooperate to drive cell proliferation in both pancreatic and cervical cancer." (PMID 35350378, 2022). "But the study also revealed an interesting point, i.e., the overexpression of oncogenic factors E2F1 and Myc can also counteract the proliferation or migration of cervical cancer cells induced by the lack of FTO, and weaken its inhibitory effect." (PMID 34149432, 2021). "Additionally, FTO reduced m6A and stabilized HOXC13-AS thus up-regulating FZD6 and activating Wnt/β-catenin signaling to drive cervical cancer cell proliferation, invasion and epithelial mesenchymal transition, suggesting HOXC13-AS as a potential target for cervical cancer treatment." (PMID 37365581, 2023). "The migration assay also revealed that demethylation activity of FTO was required to regulate cell movement as overexpression of FTO-WT but not FTO-Mut could efficiently increase cervical cancer cells’ migration." (PMID 31827395, 2019). "In the present study, we showed that FTO was frequently overexpressed in cervical cancer tissues and positively correlated with tumorigenesis, functional FTO but not mutant FTO without demethylase activity could regulate cervical cancer cells’ proliferation and migration." (PMID 31827395, 2019).